CD4 (CD4 molecule)
Diseases named in the same sentence as CD4 in open-access papers (continued):
Sharing a sentence is not in itself a finding about the gene and the disease.
asthma (continued). "The findings regarding TSLP and human asthma align with the mouse model, as TSLP promotes the proliferation of CD4+ T cells and enhances Type 2 cytokine production." (PMID 41568067, 2026). "Neutrophilic infiltration is driven by increased IFNγ and/or IL‐17A production, and IFNγ and IL‐17A were increased in bronchoalveolar lavage (BAL) fluid and in CD4 and CD8 T cells of patients with severe asthma compared to controls or milder asthma phenotypes." (PMID 41508394, 2026). "In contrast, in CD4 cluster 9, we observed a lower frequency of CD4+ KLRG1+ cells among TCM cells in T2 asthma compared to non‐T2 asthma." (PMID 40965120, 2025). "↑ T lymphocytes (CD3+), Treg (CD4+CD25+FOXP3+), Tc (CD8+), and NK cells (CD3–CD16+CD56+). ↓ activated T cells (CD25+/CD69+). ↑ immune modulation in asthma." (PMID 40352259, 2025). "Research has indicated significant infiltration of CD4+T cells in bronchial biopsies and lung tissue samples from patients with COPD and asthma." (PMID 40433386, 2025). "NECs cannot avoid transmitting information via CD4+CD25+Foxp3+ Tregs through TSLP/TSLPR, similar to the lower airway in asthma." (PMID 40051629, 2025). "Studies have shown that qigong exercises can enhance the immune system of the body and increase the CD4+ indicators in peripheral blood, thereby increasing FEV1, reducing airway inflammation, and improving the symptoms of asthma patients." (PMID 40443451, 2025). "Our study proposes specifically targeting CD4+ T cells as a therapeutic strategy to attenuate AHR and lung inflammation in steroid-resistant asthma." (PMID 40226621, 2025). "TRPA1 has also been found to be highly expressed in CD4+ T cells within the lung tissue of C57BL/6 mouse asthma models, with expression levels increasing with asthma severity." (PMID 40678720, 2025). "Traditionally, one would anticipate a 3-4:1 ratio of CD4 T cells to CD8 T cells in circulation, but in the case of the males with asthma this ratio was lower in comparison to females with asthma." (PMID 40821845, 2025). "Further classification excluding CD4+ T and CD8+ T cell types revealed a significant increase in CD14+ monocytes and a significant decrease in CD16+ monocytes among asthma patients compared with healthy controls." (PMID 41550933, 2025). "RORC is required for naive CD4+ T cells to differentiate into Th17 lymphocytes; RORC mRNA expression is higher in obesity-related asthma, while methylation of the RORC promoter is lower." (PMID 39858200, 2025). "Further research is needed to determine if pDCs have more roles in asthma beyond their known IFN-λ secretion, which counteracts IL-4’s impact on CD4+ T cells." (PMID 39530090, 2024). "Our results showed that, during acute asthma exacerbation, hsa‐miR‐155‐5p in AEC‐Exos regulates the differentiation of CD4+ T cells into Th2 type inflammation through the SIRT1 pathway, which was mediated through enhanced expression of STAT6 and GATA3." (PMID 38938285, 2024). "DNAm significantly impacts CD4+ T cells, affecting activation and repressing IFNG gene expression during experimental asthma." (PMID 38965641, 2024). "In this study, we determined the role of CD4+ TRMs in RSV-infected asthma and how the transcription factor PLZF regulates CD4+ TRMs and affects chronic inflammation in asthma." (PMID 39632661, 2024). "We demonstrate an increase in the number and proportions of lymphocytes and CD8 + T-cells in the large airways, and a decrease in the proportions of CD4 + T-cells in adults with a history of BPD compared to healthy control subjects and patients with asthma." (PMID 38336805, 2024). "Several reports have suggested that CD4+CD44+ memory T cells are involved in RSV infection and asthma." (PMID 39632661, 2024). "We observed that CD4+ T cells from AEA patients in LPP preferentially differentiate into Th1 phenotype upon activation, indicating its potential involvement in asthma pathophysiology." (PMID 39403120, 2024).
asthma (continued). "CD4+CD44+ T cells are closely related to the severity of asthma aggravated by RSV infection, and among the memory T cells, the enrichment of CD4+ TRMs in the lungs is the dominant change, which promotes the recurrence of early asthmatic pulmonary inflammation." (PMID 39632661, 2024). "In patients with asthma, the number of CD103+CD4+ TRM cells with cytotoxicity and proinflammatory cytokines increases with disease severity." (PMID 39193473, 2024). "We collected peripheral blood samples from clinical childhood asthma cases and healthy controls, and determined c-CBL expression in CD4 + T cells." (PMID 39342146, 2024). "Asthma was induced in neonatal mice by ovalbumin (OVA) intraperitoneal injection and aerosol inhalation, and c-CBL expression in CD4 + T cells from peripheral blood and spleen was measured." (PMID 39342146, 2024). "In the present study, we collected peripheral blood from childhood asthma cases and healthy controls, and found that c-CBL was downregulated in the CD4 + T cells from asthmatic children." (PMID 39342146, 2024). "Concretely, hsa‐miR‐155‐5p was transported from AEC‐Exos to CD4+ T cells through SIRT1‐mediated pathway, which further induce the enhanced Th2 inflammation in acute asthma exacerbation after RSV infection." (PMID 38938285, 2024). "A/PR8 influenza virus infection aggregated the exhaustion of CD4 and CD8 T-cells, and their percentages were significantly higher in asthma-infected mice than in naïve-infected mice." (PMID 37424011, 2023). "There are other miRNAs associated with the pathology of asthma and allergies, such as miR-21, which targets IL-12p35 in steroid-resistant asthma; miR-1248, which targets IL-5; and miR-15a, which inhibits VEGFA in CD4 + cells." (PMID 37605155, 2023). "Levels of CD3, CD4, and CD45 absolute count, CD4/CD8, and B cell (CD19 percentage and absolute count) were higher in the asthmatic bronchitis group than in the asthma groups, while levels of CD3, CD8, and CD16CD56 percentage were lower (p < 0.05)." (PMID 37893483, 2023). "In this prospective study, the proportion of PD-1 + CD4 + as well as PD-1 + CD8 + T cells in BAL samples, isolated from patients with lung cancer, asthma or interstitial lung disease (ILD), were determined via flow cytometry and compared for differences." (PMID 37535195, 2023). "The ratio of Th2/Th1 cells to CD4 T-cells significantly increased, indicating that OVA-induced asthma elicited Th2-biased T-cell differentiation." (PMID 37424011, 2023). "(D–I) Cd4-CreAccl1fl/fl mice and the Acc1fl/fl control mice were subjected to OVA-induced asthma (D–F) or house-dust mite (HDM)-induced asthma (G–I)." (PMID 37917548, 2023). "The increase in CD11b+ DC activity and numbers of CD4+ T cells should be further investigated as allergen-specific CD4+ T cells are known drivers of allergic pulmonary responses, which may implicate the contribution of V. victoriae on allergic airway diseases such as asthma." (PMID 36864880, 2023). "The top 5 immune cell subtypes with the highest infiltration proportion in the asthma group were macrophages M2, mast cells resting, T-cell CD8, plasma cells, and T-cell CD4 memory resting." (PMID 36843917, 2023). "The percentages of exhausted CD4 and CD8 T-cells in the naïve-infection group were marginally higher than those in the control group, yet lower than those in the asthma group." (PMID 37424011, 2023). "Studies have shown that CD4 tissue resident memory T cells (TRM) are responsible for the existence and recurrence of asthma, and that CD8 TRM also play an important role in the recruitment of immune cells to the lungs, especially in chronic cases." (PMID 37415170, 2023). "A significant difference in the proportion of PD-1 + CD4 + cells was found between patients with ILD and asthma (p = 0.04)." (PMID 37535195, 2023).
asthma (continued). "Although most studies focus on the clinical efficacy, Omalizumab therapy has been shown to reduce peripheral blood eosinophilia and restore numbers of CD4+Foxp3+CD25+CD127lo Treg, correlating with the level of asthma control." (PMID 37163370, 2023). "In a murine asthma model, oral administration of PCBL induced an increase in the number of CD4+CD25+FOXP3+ lymphocytes in intestinal lamina propria and respiratory tract mucosa." (PMID 35812388, 2022). "AYC-EV (8 mg/kg)-treated asthma-induced mice (G4) showed decreased levels of IFN-γ+CD4+, IL-5+CD4+, IL-17A+CD4+, and IL-5+IL-17A+CD4+ T cells as compared to the disease-causing groups (G2)." (PMID 36139376, 2022). "It is well-known that IL-4, IL-5, and IL-13 cytokines produced by CD4+ natural killer T cells and CD4+ T MHCII-restricted cells enhance eosinophilia and increase the severity of asthma." (PMID 35733161, 2022). "In a mouse model of asthma, TGF-β induces the expression of the transcription factor Foxp3 to convert peripheral CD4+CD25− naïve T cells into CD4+CD25+ regulatory T cells and thereby reduces allergic responses in the lungs." (PMID 36225183, 2022). "The FlowSOM algorithm was further used to cluster, visualize, and compare the differences of CD3+CD4+T cells among the ABPA, A.f (+)-asthma patients, and HDM (+)-asthma patients before and after exposure." (PMID 35983066, 2022). "Although SGK1 was found to be upregulated in individuals with asthma, SGK1 and miR-19a in CD4+ T cells appear to have a common regulatory relationship, independent of the disease." (PMID 36611927, 2022). "The key finding was that maternal high-fat diet during pregnancy enhanced CD4+ T-cell activation, proliferation and TH2 skewing in offspring, thus promoting asthma development." (PMID 35745240, 2022). "To distinguish the effects of LF in the population of T cells in OVA-induced asthma, we used Foxp3, IL-4, INF-γ, and CD4 antibodies to evaluate the differentiation of T cells." (PMID 36430662, 2022). "γδ T cells are also involved in asthma pathogenesis and Th2 inflammation through IL-17 production, and this trend is considered to be similar to that of CD27-negative CD4+ T cells." (PMID 35454107, 2022). "We therefore examined in situ LCK(Y505) phosphorylation in CD4+ T cells from the lung sections obtained from our mouse asthma model and observed increased phospho-LCK (Y505) staining in CD4+ T cells from Asp-challenged Spry2−/− mice." (PMID 33684096, 2021). "Recruitment of CD4+ T cells and eosinophils was abnormally higher in ACO mice, indicating a stronger tendency of asthma, whereas B cells, macrophages, and dendritic cells showed more robust activation." (PMID 33869177, 2021). "Beta (95% CI) per standard deviation of CD4+ Ki-67, FKBP51, and dexamethasone-induced FKBP51 expression to asthma control and lung function in obese and normal weight participants with asthma." (PMID 34721414, 2021). "First, we demonstrated distinct changes in their expression on airway inflammatory cells in asthma, e.g., upregulated α1 subunit on BAL CD4+ T-cells, which suggests their activation and potential priming for binding to ECM components." (PMID 34204767, 2021). "The intraperitoneal transfer of DClps inhibited the development of Th2 allergic responses by increasing Tregs, suppressing CD4+ memory T cells and decreasing STAT6 phosphorylation level in OVA-induced asthma models." (PMID 34093516, 2021). "We found that there were significant differences in wheezing frequency,level of CD4+CCR6+CRTh2+ memory Th2 cells and API between children diagnosed with asthma and children with non-asthma outcomes." (PMID 34090369, 2021). "This study identifies increased prevalence of a distinct CD4+ subset-expressing FKBP51 and Ki-67 in obese children with asthma compared with a matched sample of normal weight children with asthma." (PMID 34721414, 2021). "The expression level of Spry2 in CD4+ T cells from blood and BAL was significantly higher in patients with asthma." (PMID 33684096, 2021).
asthma (continued). "In contrast, the frequency of Th17 cells in the lung, as well as the production of IL-17 by CD4+ T cells, was significantly higher in the lungs of mice with neutrophilic (CFA/OVA) than with eosinophilic (Alum/OVA) asthma." (PMID 34061861, 2021). "Statistical methods were used to determine the correlation between the level of circulating CD4+CCR6+CRTh2+ memory Th2 cells and a diagnosis of asthma, thereby providing a theoretical basis for the early diagnosis of asthma in children." (PMID 34090369, 2021). "The results indicated that circulation CD4+CCR6+CRTh2+ memory Th2 cells displayed higher specificity and PPV in predicting asthma diagnosis." (PMID 34090369, 2021). "On the other hand, patients with severe asthma have reduced IFN-γ production, which promotes differentiation of CD4+T-cells into Th2 cells." (PMID 34305927, 2021). "Previous studies have shown that luteolin affects asthma via the induction of FOXP3+ and CD4+CD25+ Tregs or acts as an immunosuppressant mTOR inhibitor to increase the percentage of CD4+FOXP3+ Tregs posttransplantation." (PMID 33532509, 2021). "PSA is able to induce abscess and adhesion formation in sepsis models, but can also inhibit asthma, inflammatory bowel disease (IBD) and experimental autoimmune encephalomyelitis (EAE) through MHCII-dependent activation of CD4+ T cells." (PMID 33193325, 2020). "In conclusion, this investigation tentatively verified that ozone exacerbated asthma development by activating PVT1-miR-15a-5p/miR-29c-3p signaling, which motivated Th1/Th2 imbalance of CD4+ T cells and urged excessive proliferation of ASMCs." (PMID 33223504, 2020). "In the present study, we detected CD4+ T cells and MDSC subsets and evaluated the relationship of these cells in mice with ovalbumin-induced asthma." (PMID 32549755, 2020). "From these findings, we might hypothesize that in patients carrying 17q12–21 asthma risk SNPs, dynamic changes in the expression and action of key ER SERCA pumps in response to T cell receptor (TCR) activation would be hindered by higher ORMDL3 expression in CD4+ T cells." (PMID 33424845, 2020). "Our study newly introduced that PI3K/Akt/mTOR signaling not merely diminished the effect of miR-15a-5p on Th1/Th2 balance in CD4+ T cells, but also undermined the impact of miR-29c-3p on ASMC proliferation, which expanded knowledge about asthma pathogenesis." (PMID 33223504, 2020). "We have previously suggested that “% of CD4+CRTh2+T cells” and “% of CD14++CD16+PAR-2+ monocytes” are biomarkers of asthma severity." (PMID 31168305, 2019). "The proportion of activated T cells (CD4+, CD25+) was increased in the lungs of the asthma group compared to that of the control group." (PMID 30783201, 2019). "In conclusion, ex vivo-generated, CD4 T cell-converted, allergen peptide-primed DNT cells exerted potent antigen-specific immune regulatory effects in allergen-induced mouse asthma models." (PMID 31534137, 2019). "Therefore, our present study suggested that it is likely that intraperitoneal administration of α‐GalCer prior to the development of asthma disorder, which can promote the generation of lung CD4+ FoxP3+ Treg cells by the activated iNKT cells, may have potential as a therapeutic method for asthma." (PMID 30421497, 2019). "The in vivo transfer of CD4+CD25+Treg cells was previously shown to inhibit AHR and Th2-mediated airway inflammation in a mouse model of asthma." (PMID 30873032, 2019). "CD4+ CD25+ regulatory T cells (Tregs) play a vital role in the regulation of immune function and their roles in asthma pathogenesis are increasingly recognized." (PMID 30909474, 2019). "IL-33 induces allergic diseases, such as asthma, through the activation of various immune cells that express an IL-33 receptor, ST2, including ST2+ memory (CD62LlowCD44hi) CD4+ T cells." (PMID 30972065, 2019). "MSCs appeared to have a suppressive function that affected CD4+ and CD8+T cell activation and proliferation in children with asthma." (PMID 31673233, 2019).
asthma (continued). "They used flow cytometry to reveal a decrease in the CD4+CD25+ Treg ratio of CD4+ T cells and function in the PBMCs of patients with asthma." (PMID 31826046, 2018). "We found that the frequencies of GATA3+IL-4+, GATA3+IL-5+, and GATA3+IL-13+ CD4+ T-cells in the lungs of asthma-induced Bcl11bfl/fl dLck-iCre mice were reduced, as were the frequencies of GATA3+, IL-4+, IL5+, and IL-13+ CD4+ T-cells." (PMID 29700302, 2018). "The immunization induced antigen-specific CD4+CD25− asTregs and prevented the host from OVA sensitization-induced asthma." (PMID 28638384, 2017). "The importance of neonatal pTregs in asthma prevention is based on the observation that the cytokines IL-4 and IL-6 inhibit FOXP3 expression in naive CD4+ T cells." (PMID 28589115, 2017). "In asthma/A(H1N1)pdm09 group, the number of CD4+ cells at 3 days and CD8+ cells at 7 days post-infection were higher than those of other groups, respectively." (PMID 28831046, 2017). "Furthermore, RSV infection could augment CD3 and CD4 expressions in RSV-infected asthma mice." (PMID 29123203, 2017). "The expressions of CD3 and CD4 protein were increased in RSV-infected mice and asthma mice compared with control mice." (PMID 29123203, 2017). "Patients with asthma have increased number of CD4 + T lymphocytes, decreased CD8+ T cells as well as higher ratios of CD4+/CD8+." (PMID 28257632, 2017). "The aim of these experiments was to demonstrate the importance of CD4+ T cells and the role of TRPV1 in an asthma model using a clinically ready TRPV1 inhibitor (XEN-D0501) and genetically modified (GM) animals." (PMID 27255083, 2016). "The increase of the absolute number of CD3+CD4+ lymphocytes in patients with COPD compared with the control group, patients with asthma and ACOS (p1-2 = 0.000001, p2-3 = 0.000010, and p2-4 = 0.0000132, resp)." (PMID 27660519, 2016). "In the prevention group, IL-27 was administered before OVA sensitization when the CD4+ T cells were largely naïve and could be promoted to differentiate into Th1 cells by IL-27, supporting an environment of Th1 cells before the asthma challenge could alleviate the onset of an asthma attack." (PMID 27687913, 2016). "Research over the last three decades has provided evidence that T helper 2 (Th2) CD4+ T cells are a major contributor to the development of AAD in animals and asthma in humans." (PMID 27601994, 2016). "This CD4+/CD8+ T cell dependent, HDM driven model of allergic asthma exhibits key features of asthma." (PMID 27112462, 2016). "The most important difference between asthma and COPD is the nature of the inflammation, which is primarily eosinophilic and CD4-driven in asthma, and neutrophilic and CD8-driven in COPD." (PMID 26819713, 2015). "CD4+CD25+ T cells also play an important role in suppressing airway eosinophilic inflammation and in the development of airway hyperreactivity in asthma." (PMID 26176545, 2015). "We previously reported that the percentage of CD4+ T cells producing IL-17 and IL-22 (Th17 cells) is significantly greater in patients with active EGPA than in healthy controls or in patients with asthma, chronic eosinophilic pneumonia, or inactive EGPA." (PMID 25174446, 2014). "Interestingly, vitamin D may protect from developing respiratory infections that could serve as trigger for a deterioration of asthma and is potentially capable of overcoming the poor glucocorticoid responsiveness in severe asthmatics by upregulation of IL-10 production from CD4+ T cells." (PMID 25061262, 2014). "Recent evidence indicates that CD4+CD25highFOXP3+ Tregs and TH17 cells play an important role in mediating asthma." (PMID 24995020, 2014). "Infiltration of CD4+ Th cells, which are important in the pathogenesis of asthma, was much more increased than that of CD8+ T cells in the OVA-induced asthma model, and this response was also suppressed by ACA." (PMID 23451048, 2013).